MMP2 (matrix metallopeptidase 2)
Diseases named in the same sentence as MMP2 in open-access papers (continued):
Sharing a sentence is not in itself a finding about the gene and the disease.
liver fibrosis (continued). "Western blot analysis of liver fibrosis markers revealed that Huangqi Decoction significantly reduced the expression levels of alpha-smooth muscle actin (α-SMA), type I collagen, matrix metalloproteinase-2 (MMP-2), and matrix metalloproteinase-9 (MMP-9)." (PMID 39388703, 2025). "In addition, PNVs and EA mitigated hepatic fibrosis, as indicated by Sirius red staining and the reduced levels of TGF, α‐SMA, and MMP2 in WD‐mediated MASLD." (PMID 40212474, 2025). "API effectively alleviates CCl4-and bile duct ligation (BDL)-induced liver fibrosis by reducing liver enzyme levels, inhibiting ECM production, and regulating the balance between matrix metalloproteinase 2 (MMP2) and tissue inhibitors of metalloproteinase 1 (TIMP1)." (PMID 39749193, 2024). "Additionally, increased MDA levels and decreased TAC and GPX levels pointed to lipid peroxidation, while upregulation of MMP2 and MMP9 indicated liver fibrosis progression." (PMID 39185304, 2024). "Because ANTXR2 promoted the activation of MMP2 to degrade the ECM, whether ANTXR2 overexpression might alleviate liver fibrosis was investigated." (PMID 38322497, 2023). "On the other hand, AECs reduced collagen synthesis in human hepatic stellate cells with paracrine effect, and some soluble factors like MMP-2/9 were secreted by AECs, enhancing ECM remodeling, reducing liver fibrosis, and altering macrophage polarization, particularly in liver fibrosis models." (PMID 37711653, 2023). "Many predicted targets such as TIMP1, MMP2, COL1A1, MMP7, and COL3A1 have been involved in liver fibrogenesis and could be potential therapeutic targets for liver fibrosis." (PMID 35791909, 2022). "In the liver fibrosis model, the expression of MMP-9 was higher than in the normal group, probably due to the synergy between MMP-9 and MMP-2 in restoring the structural integrity of liver cells and maintaining the normal morphology of the basement membrane of the liver sinusoids." (PMID 35883127, 2022). "TIMP-1 and -2 block MMPs such as MMP-2 and MMP-9, which are involved in inhibiting liver fibrosis." (PMID 36232681, 2022). "We did not observe the same decrease in MMP activity although Mmp2 expression was increased and is reported to be increased and have a profibrogenic role in liver fibrosis." (PMID 35341737, 2022). "We further demonstrated that miR-6676-3p downregulated the mRNA expression of α-SMA, COLLAGEN I, TIMP1, TIMP3 and upregulated MMP2, MMP9, which are all profibrogenic genes in which TIMP1/3 antagonize MMP2/9 which decompose the collagen I during the progression of liver fibrosis." (PMID 34930304, 2021). "In addition, the staining of other HSCs activation related proteins TGF-β1, MMP-2, and TIMP-2 were more pronounced in the livers of CCl4-induced liver fibrosis mice than that in the control." (PMID 34603071, 2021). "RT-PCR revealed that infusion of either the control or miR-150 secretome significantly reduced the mRNA expression levels of MMP-2, α-SMA, and TGF-β1 in the liver compared to those of infusion of normal saline, particularly in mice with liver fibrosis (P < 0.05)." (PMID 32152450, 2020). "Also, incubating LX2 cells with either GDF11 or TGF-β for 24 h led to significantly elevated mRNA levels of MMP2, αSMA/ACTA2, Col1A1 and Col5A1 — markers for stellate cell activation and liver fibrosis." (PMID 33126224, 2020). "Moreover, NEMOΔhepa/Faslpr animals elicited significantly decreased parameters of liver fibrosis, such as Collagen IA1, MMP2, and TIMP1, and reduced proinflammatory macrophages and cytokine expression." (PMID 30737368, 2019). "In a model of murine liver fibrosis induced by carbon tetrachloride (CCl4), administration of PRI-724 (the inhibitor of CBP/β-catenin interaction) accelerated the resolution of liver fibrosis accompanied by an increase in MMP-9, MMP-2, and MMP-8 levels in intrahepatic leukocytes." (PMID 30308992, 2018).
liver fibrosis (continued). "In turn, AESN may delay and inhibit the progression of hepatic fibrosis, including α-smooth muscle actin (α-SMA) inhibition and MMP-2 production." (PMID 26927042, 2016). "Both MMP2 and TIMP1 regulate the process of liver fibrosis via TGF-β1 mediation." (PMID 26378522, 2015). "During hepatic fibrosis, leptin suppresses the expression and activity of the collagen-degrading MMPs, such as MMP2, and promotes the expression of TIMP1, an important negative regulator of MMP2." (PMID 24982243, 2014). "Particularly, MMP2 and TIMP1 are expressed primarily in liver fibrosis." (PMID 24860243, 2014). "In liver fibrosis and cirrhosis, transforming growth factor-β1 (TGF-β1) stimulates CD147 overexpression, which induces collagen I and MMP-2 secretion to promote hepatic stellate cell activation, while CD147 expression decreased during spontaneous recovery from liver fibrosis." (PMID 25268615, 2014). "With the improvement in liver fibrosis, the mRNA levels of tissue inhibitor of metalloproteinase-1 (TIMP-1) and matrix metalloproteinase-2 (MMP-2), two genes involved in hepatic fibrogenesis, were found to be significantly suppressed, while TIMP-2 and MMP-13 were unaffected." (PMID 24066058, 2013). "In contrast to that, our findings show that PZQ alone seemed to be effective in reducing hepatic fibrosis as shown by a clear reduction in the serum levels and tissue expression of TGF-β1 and MMP-2, the number of mast cells and hepatic HYP content at 10 and 18 weeks PI." (PMID 22236605, 2012). "Thereby a fragment of type III collagen generated in vitro by MMP-2 and MMP-9 may be a biochemical marker for liver fibrosis." (PMID 23249435, 2012). "Furthermore, MMP-2 has been shown to induce the release of VEGF, which is involved in hepatic sinusoidal capillarization and promotes the development of liver fibrosis." (PMID 21731450, 2011). "For this purpose, we employed five serum biological markers (TGF-β1, collagen IV, MMP-2, laminin and EGF-R) which are assumed to reflect the degree of liver fibrosis and compared these markers in 50 pediatric patients with chronic liver diseases to 30 healthy controls." (PMID 27942306, 2010). "Additionally, TCSO markedly downregulated the expression of key fibrogenic proteins, such as transforming growth factor-β1 (TGF-β1), matrix metalloproteinase-2 (MMP-2), and tissue inhibitor of metalloproteinases-1 (TIMP-1), thereby effectively suppressing the progression of hepatic fibrosis." (PMID 41823869, 2026). "The CCl4-induced liver fibrosis mouse model showed that the administration of α-mangostin significantly decreased the expression of the fibrosis markers (α-SMA, collagen-a2 (col1a2), desmin and matrix metalloproteinase-2 (MMP-2)) as well as attenuated hepatic collagen deposition and liver damage." (PMID 37760177, 2023). "Additionally, MMP2, MMP3, and MMP9 are highly expressed during the acute phase of tissue damage, and the role of MMP12 in the treatment of mesenchymal stem cells for liver fibrosis has been reported." (PMID 37189708, 2023). "CCl4 injection resulted in liver fibrosis with a more pronounced effect in Parkin-/- mice, as shown by the hepatic mRNA levels of markers for hepatic stellate cell (HSC) activation and fibrosis (Col1a1, Acta22, and Mmp2) as well as Masson and Sirius red staining." (PMID 36658227, 2023). "The enhanced generation and secretion of MMP-2 and some measure of MMP-9 after treatment with 5 μM CBG of hepatocytes exposed to palmitate and fructose solution might contribute to the reduction in experimental hepatic fibrosis." (PMID 37759466, 2023). "Decreases ALT, AST and ALP levels; down-regulates α-SMA, type I collagen, fibrotic factor-CTGF, MMP2 and MMP9; inhibits the activation of the transforming growth factor-β-1/Smad pathway and hepatic stellate cells mediated by transforming growth factor-β1; and prevents liver fibrosis." (PMID 35566359, 2022).
liver fibrosis (continued). "Furthermore, leptin promotes the synthesis of the matrix metalloproteinase-2 (MMP-2), tissue inhibitor matrix metalloproteinase 1 (TIMP-1), TIMP-2, and alpha-smooth muscle actin (α-SMA) transcripts, all involved in the pathogenesis of liver fibrosis." (PMID 33800465, 2021). "MiR-31 may also mediate liver fibrosis by promoting HSC activation and enhancing MMP-2 expression." (PMID 28538690, 2017). "However, during liver fibrosis resolution, as TIMP expression declines, the persistence of MMP-2 may permit collagen degradation." (PMID 23829789, 2013). "Furthermore, the severity of hepatic fibrosis was positively correlated with the level of SRD5A2 expression, suggesting that an elevated level of SRD5A2 expression may promote the development of fibrosis by reducing MMP-2 activity and impairing the degradation of extrahepatic matrix proteins." (PMID 37784175, 2023). "We measured MMP-2, MMP-9, and their inhibitors (TIMP-1, TIMP-2) in the CCl4-induced liver fibrosis group with/without UCB-Exo treatment." (PMID 34772443, 2021). "In the current study, we found that a nonselective MMP inhibitor, MMP‐2/MMP‐9 inhibitor and MMP‐9 gene deletion consistently attenuated liver fibrosis in the BDL animal model." (PMID 34647412, 2021). "Second, a cut-off value could not be defined for CK-18 M30 and MMP-2 levels.In conclusion, our study indicated that CK-18 M30 and MMP-2 levels are higher in CHB patients compared to healthy controls and are associated with significant hepatic fibrosis, especially cirrhosis." (PMID 24032040, 2013). "However, these subtle increases in MMP-2 and MMP-13 expression after reconstitution with VHLfl/fl/VEGFfl/fl-LysMCre+ BM, although statistically significant, are obviously not sufficient to accelerate the resolution of liver fibrosis." (PMID 28118605, 2017). "Thus current results suggested that MMP2, MMP9 and TNF-α could be considered as potential markers of inflammation but not of the degree of liver fibrosis in chronic HCV patients." (PMID 26464613, 2015).
colon carcinoma (195 papers, 2001 to 2026). "Recently, the GSN level was also found elevated in colon cancer and associated with tumor invasion signaling pathways such as MMP-2/MMP-9 and the MAPK and TGF-β pathways." (PMID 35804959, 2022). "MMP-2 and MMP-9, known as gelatinase A and B, are critically involved in tumor invasion and metastasis and their expression has been associated with poor overall survival in patients with colon cancer." (PMID 34885656, 2021). "In particular, the level of active MMP2 associated with tumor cells located within the invasive regions of colon cancer specimens was increased 10-fold over the level of active MMP2 associated with adjacent normal epithelium within the same tumor specimens." (PMID 34830271, 2021). "GA has also been shown to activate AMPK in SW480 colon cancer cells and to decrease expression of invasion-associated proteins, including matrix metalloproteinase (MMP)-2, MMP-9, urinary-type plasminogen activator (uPa), and C-X-C chemokine receptor type 4 (CXCR4) in the SW480 cells." (PMID 34681204, 2021). "Analyzes of rs243865 in MMP-2 in 2 studies conducted in Saudi Arabia comprising 220 cases and 247 controls revealed positive correlation of TT genotype with 6.5- fold increased risk of colon cancer." (PMID 32765800, 2020). "Since MMP-2, -7 and -9 have been associated with different aspects of colon cancer, we assessed whether IGF-1 and PPP could affect their protein expression in the HT-29 cell line." (PMID 22159423, 2012). "Furthermore, many reports have indicated that increased MMP-2 activity was observed in human tumor cell lines displaying an invasive phenotype and was associated with the metastatic potential of breast and colon carcinomas, supporting the essential role of MMP-2 in tumor invasion." (PMID 18426555, 2008). "In colon cancer cells, miR-22 transfection has been reported to significantly reduce the expression of MMP-2 and MMP-9." (PMID 41583211, 2025). "In a mouse lung metastasis model, AAM can reduce the lung metastasis ability of colon cancer cells by downregulating the activation of the HIF-1α/MMP2 signaling pathway." (PMID 40563539, 2025). "Collectively, our data indicate that PLE0 exerts an anti-metastatic effect in human colon cancer cells by inhibiting epithelial–mesenchymal transition and MMP-2/9 via downregulation of GSK3β/β-catenin and JNK signaling." (PMID 38732748, 2024). "The effect of Lut on MMP-2 and MMP-9 in the development of colon cancer was induced by azoxymethane (AOM) in BALB/c mice to investigate impacts of Lut on MMP-2 and MMP-9." (PMID 38672151, 2024). "The assessment of colon tumor invasion and metastatic potential involved the examination and analysis of MMP-2 expression." (PMID 38535948, 2024). "This reduction in DBN1S142p resulted in increased binding of ACTN4 to F-actin, thereby stabilizing F-actin and ultimately leading to reduced MMP2 expression and inhibition of colon cancer cell migration." (PMID 39052867, 2024). "This, in turn, enhances the binding of ACTN4 to F-actin and stabilizes F-actin, ultimately resulting in reduced MMP2 expression and decreased migratory ability in colon cancer cells." (PMID 39052867, 2024). "Inhibits cell migration by decreasing the expression of urokinase plasminogen activator (u‐PA), tissue‐type plasminogen activator (t‐PA) and matrix metalloproteinase 9 (MMP‐9) as well as matrix metalloproteinase 2/9 (MMP‐2/9) activity in colon cancer cells." (PMID 36207986, 2023). "In some specific breast and colon cancer cell lines, ROS production also increased the expression of matrix metalloproteinases (MMP)-2 and -9, enzymes that degrade the extracellular matrix and are involved in cell invasion and metastasis." (PMID 36674555, 2023). "Our analyzed data showed that colon cancer patients with the high co-expression of TMEM211/MMP2 or TMEM211/MMP9 had poor DSS." (PMID 37367036, 2023).
colon carcinoma (continued). "Auraptene has been reported to suppress matrix metalloproteinase (MMP)-2, MMP-7, and MMP-9 expression in human colon cancer cells, as well as MMP-2 and MMP-9 activity, to inhibit the migration and invasion of cancer cells." (PMID 37447286, 2023). "Carvacrol suppresses the expressions of matrix metalloproteinase-2/9 (MMP2/9) and triggers cell cycle arrest in G2/M phase and apoptosis to inhibit colon cancer proliferation." (PMID 36983900, 2023). "A previous study revealed that ethanol mediated both the activation of Nrf2 and HO-1 to maintain colon cancer cell survival through matrix metallopeptidase 2 (MMP2), MMP9 and VEGF, thus leading to a more aggressive phenotype." (PMID 35417854, 2022). "In a previous study, aloe emodin inhibited colon cancer cell migration/angiogenesis by downregulating MMP-2/9, RhoB, and VEGF." (PMID 36212129, 2022). "The results showed that TMP can effectively reduce the activities of MMP-2 and 9 in all the tested human colon cancer cells." (PMID 35883447, 2022). "FN suppresses cell proliferation and invasion by inhibition of cyclin D1 and MMP2/9 expression via p-STAT3 inactivation in colon carcinoma cells." (PMID 34539403, 2021). "In colon cancer, FABP4 enhances epithelial–mesenchymal transition and the associated proteins, including MMP-2, MMP-9, and E-cadherin via the AKT pathway." (PMID 34685761, 2021). "Isoalvaxanthone, a natural xanthone derivative isolated from plants, also had similar activities in SW620 colon cancer cells, additionally inhibiting Rac1 factor and subsequently reducing the expression and activity of MMP-2 and MMP-9." (PMID 34680113, 2021). "The majority of the colon cancer tissues showed lytic activities corresponding to the latent and activated forms of MMP2 and MMP9." (PMID 34830271, 2021). "In summary, we identified MMP-2 regulatory proteins by collecting concordant evidence between the secretome of HCT116 colon cancer cells, the CRC patient plasma, and tissue proteomes." (PMID 34429501, 2021). "A densitometric quantification of Pro-MMP9 and Pro-MMP2 in all analyzed samples confirmed statistical differences between colon cancer tissues and paired normal tissues." (PMID 34830271, 2021). "Research has demonstrated that other phenolic acids found in BGN such as caffeic acid phenyl ester (CAPE) and caffeic acid not only inhibited the invasion of colon cancer cells but equally brought about a reduction in MMP-2/-9 and VEGF production." (PMID 34901488, 2021). "The expression of matrix metalloproteinase-2 (MMP-2) has been linked to invasive metastasis in various neoplasia including ovarian, breast, and colon carcinoma." (PMID 33287452, 2020). "H. pylori infection also decreased the MMP2 expression related to TAMs, and thereby H. pylori infection can limit colonic tumor metastasis." (PMID 33201893, 2020). "Expression of MMP‐2 has shown to be correlated with poor prognosis in colon cancer patients and enhanced motility of tumor cells." (PMID 32652895, 2020). "In our study, the EMT phenotype markers changed significantly in FABP4-overexpressed colon cancer cells: the upregulation of Snail, MMP-2 and MMP-9, as well as the downregulation of E-cadherin." (PMID 33088219, 2020). "RT-PCR was conducted to determine the relative expression levels of miR-518c-5p and MMP2 in the colon cancer cell lines." (PMID 32158464, 2020). "Different studies have shown that MMP-2 contributes to the migration and metastasis of colon cancer cells." (PMID 33330466, 2020). "This activity is possible because colon cancer cells produce matrix metalloproteinase 2 (MMP-2) and matrix metalloproteinase 9 (MMP-9), gelatinases which dissolve type IV collagen, the essential component of BM." (PMID 32403316, 2020). "Rosmarinic acid inhibited colon cancer invasion and colorectal cancer metastasis by inhibiting MMP-2 and MMP-9 activity." (PMID 32102512, 2020).